BRIP1 (BRCA1 interacting DNA helicase 1)
Diseases named in the same sentence as BRIP1 in open-access papers (continued):
Sharing a sentence is not in itself a finding about the gene and the disease.
ovarian carcinoma (continued). "Along with BRCA1 (FANCS) and BRCA2 (FANCD1), involved in hereditary breast/ovarian cancer (HBOC) syndrome, three other members of the FANC family have been associated with an increased risk of development of BrCa and/or ovarian cancer (OvCa), namely BRIP1 (FANCJ), PALB2 (FANCN) and RAD51C (FANCO)." (PMID 29659569, 2018). "Germline BRIP1 mutations, which negatively affect DNA repair and genomic stability, and thus increase the likelihood of cancer development, have been reported to be connected with breast, colon, prostate and ovarian cancer." (PMID 29466248, 2018). "BRIP1 germline mutations also confer an increased risk of ovarian cancer." (PMID 23586058, 2013). "Protein truncating mutations in BRIP1 have been identified in hereditary breast and ovarian cancer families, and a recent report suggested that a recurrent truncating mutation (R798X) may have a role in PCa susceptibility." (PMID 19935797, 2009). "The aim of this study was to evaluate whether common variants in BRIP1 are associated with breast and ovarian cancer risks using a SNP tagging approach within an association study design." (PMID 17342202, 2007). "Consequently, most patients with BRIP1-mutated platinum-sensitive stage III or stage IV high-grade ovarian cancer could already receive PARP-inhibitor maintenance therapy." (PMID 40988318, 2025). "Missense mutations in BRIP1 may increase both breast and ovarian cancer risk." (PMID 39767562, 2024). "Evidence was provided for the newer ovarian cancer-associated genes, such as RAD51C/RAD51D/BRIP1, which were associated with ovarian cancer risks of 5.8–11% and already met the requirement for risk-reducing salpingo-oophorectomy, which is recommended for patients with > 5% ovarian cancer risk." (PMID 31472684, 2019). "Similarly, although BRIP1 has been associated with only a modestly increased risk for ovarian cancer, an Icelandic mutation (c.2040_2041insTT) has been associated with an eightfold risk for ovarian cancer." (PMID 26484312, 2015). "Thus, common variants in the BRIP1 are candidates for breast and ovarian cancer susceptibility." (PMID 17342202, 2007). "Our study identified 19/728 carriers (2.6%) of pathogenic HDR gene variants, including 15 truncating variants, of which 4 were in BRCA1 or BRCA2 (0.5%) and 4 were in BRIP1 or RAD51D, two other genes associated with high ovarian cancer risk." (PMID 39440754, 2025). "BRIP1 (NM_032043.2) c.727A>G (GRCh37 chr17:59886019-T-C) was identified in a female with a personal history of ovarian cancer and a family history of ovarian, breast, and stomach cancer in first- and third-degree relatives." (PMID 41300834, 2025). "Truncating variants in BRCA1, BRCA2, BRIP1 and RAD51D represent high‐risk variants for breast or ovarian cancer." (PMID 39440754, 2025). "We aimed to investigate the GC-5′ss of the breast/ovarian cancer susceptibility genes, ATM (exon 50), BRIP1 (exon 1), and PALB2 (exon 12), and their dysregulation induced by DNA variants." (PMID 39518003, 2024). "Among such proteins whose expression is worth studying in ovarian cancer are BRIP1 (BRCA1 interacting protein C-terminal helicase 1) and also FANCI (Fanconi anemia complementation group I)." (PMID 39767562, 2024). "Immunohistochemical evaluation of FANCI and BRIP-1 (FANCJ) protein expression in ovarian cancer tissue samples was performed." (PMID 39767562, 2024). "On the other hand, the study we present is one of the first to present immunohistochemical evaluation of tissue expression of FANCI and BRIP-1 in ovarian cancer tissue." (PMID 39767562, 2024). "RAD51C, RAD51D, BRIP1, and PALB2 are genes known to be associated with a hereditary risk of ovarian cancer." (PMID 39695768, 2024).
ovarian carcinoma (continued). "Germline PVs in the HR-related genes BRIP1, PALB2, RAD51C and RAD51D have an established role in increasing a patient's risk of ovarian cancer." (PMID 36805919, 2023). "For ovarian cancer, high expression of BRIP1 was correlated to worse OS (P=0.027) and PFS (progress-free survival) (P=0.036) in patients." (PMID 36907870, 2023). "Monoallelic pathogenic variants in FANCD1/BRCA2, FANCS/BRCA1, FANCJ/BRIP1, FANCM, FANCN/PALB2, and FANCO/RAD51C have been linked to familial breast and ovarian cancer." (PMID 36428697, 2022). "Based on the studies in breast and ovarian cancer, BRCAness are present in about 20% of breast cancer and 45% of ovarian cancer, such as the mutations in RAD51C, NBS1, BRIP1, and PALB2." (PMID 36497135, 2022). "Genomic alterations that involve other genes in HR pathways, including FANCJ/BRIP1 and FANCN/PALB2, have also been suggested to increase the lifetime risk of epithelial ovarian cancer development." (PMID 35330396, 2022). "Germline mutations in BRIP1 and MPL were associated with increased ovarian cancer risks and hereditary thrombocytosis, respectively." (PMID 35428225, 2022). "The prevalence of a personal or family history of ovarian cancer among women with PVs in BRIP1, RAD51C, or RAD51D was similar to that observed for women with PVs in BRCA1 or BRCA2 in this cohort." (PMID 33926482, 2021). "Overall, testing for moderate- or high-penetrance BRCA1/2, RAD51C, RAD51D, BRIP1, and mismatch repair genes for the patients with epithelial ovarian cancer is recommended." (PMID 34207568, 2021). "Similar to BRCA2, the median age of ovarian cancer diagnosis was older for women with a PV in BRIP1 (65 years), RAD51C (62 years), or RAD51D (57 years)." (PMID 33926482, 2021). "The data presented here for BRIP1, RAD51C, and RAD51D supports previous research demonstrating an increased risk of ovarian cancer for women with PVs in these genes." (PMID 33926482, 2021). "The age at ovarian cancer diagnosis was older for women with PVs in BRIP1, RAD51C, or RAD51D, suggesting that it is safe to delay RRSO until age 45–50 in RAD51D PV carriers and possibly until age 50–55 in BRIP and RAD51C PV carriers." (PMID 33926482, 2021). "The median age at ovarian cancer diagnosis of women with a PV in BRIP1, RAD51C, or RAD51D was much older and more than three quarters of women with a PV in one of these three genes and a history of ovarian cancer was diagnosed after the age of 50." (PMID 33926482, 2021). "The meta-analysis provides evidence supporting the pathogenicity of BRIP1, RAD51C, and RAD51D mutations in relation to ovarian cancer." (PMID 32359370, 2020). "In this study, we aim to gain insight in the germline mutation spectrum of ATM, BARD1, BRIP1, ERCC4, PALB2, RAD51C and RAD51D in breast and ovarian cancer families from Spain." (PMID 32756499, 2020). "The prevalence rate of BRIP1, RAD51C, or RAD51D pathogenic variants is about 1% in women with ovarian cancer." (PMID 32733558, 2020). "Recently, several pieces of evidence showed that mutations in three genes involved in the homologous recombination DNA repair pathway, i.e., BRIP1, RAD51C, and RAD51D, are associated with a high risk of ovarian cancer." (PMID 32359370, 2020). "Based on the latest National Comprehensive Cancer Network Guideline, PALB2 is categorized as a gene associated with breast cancer risk, whereas BRIP1 and RAD51C are categorized as genes associated with ovarian cancer risk." (PMID 32269964, 2020). "Mutations in BRIP1, RAD51C, or RAD51D are associated with an increased risk of developing ovarian cancer." (PMID 32733558, 2020).
ovarian carcinoma (continued). "Monoallelic mutations in five of these genes (BRCA1, BRCA2, PALB2, BRIP1 and RAD51C) increase the susceptibility to breast/ovarian cancer and are used in clinical diagnostics as bona-fide hereditary cancer genes." (PMID 32235514, 2020). "Multiple gene panel studies have revealed that inherited breast and ovarian cancers rarely harbor germline mutations of FA genes, including BRIP1/FANCJ, PALB2/FANCN, and RAD51C/FANCO." (PMID 32269964, 2020). "Based on the best available evidence, variants in BRCA1, BRCA2, BRIP1, RAD51C, RAD51D, and the mismatch repair genes confer ovarian cancer risks that warrant the consideration of risk-reducing surgery." (PMID 33086730, 2020). "Due to their role in BRCA1/BRCA2 DNA repair pathway, the loss-of-function mutations of RAD51C, RAD51D, BRIP1, and BARD1 genes have been generally considered as ovarian cancer susceptibility genes." (PMID 31366178, 2019). "Other members of the FANCG complementation group include breast and ovarian cancer associated genes; FANCO (RAD51C), FANCS (BRCA1), BRCA2 (FANCD1), BRIP1 (FANCJ) and PALB2 (FANCN)." (PMID 28591191, 2017). "The issue is a critical one given that mutations in the Chl1 human homologs ChlR1/DDX11 and BACH1/BRIP1/FANCJ collectively result in Warsaw Breakage Syndrome, Fanconi anemia, cell aneuploidy and breast and ovarian cancers." (PMID 29186203, 2017). "Several FA genes are also breast and ovarian cancer susceptibility genes (FANCD1/BRCA2, FANCJ/BRIP1, FANCN/PALB2, FANCO/RAD51C, and FANCS/BRCA1)." (PMID 26430909, 2015). "At least 5 of the 17 known FA genes, D1/BRCA2, J/BRIP1, N/PALB2, O/RAD51C and S/BRCA1, are well-established breast and/or ovarian cancer susceptibility genes." (PMID 26085575, 2015). "As with BRCA2/FancD1, BRIP1/FancJ, and PALB2/FancN, bi-allelic mutations in RAD51C/FancO cause FA, and mono-allelic mutations increase the risk of breast and ovarian cancer." (PMID 23344037, 2013). "Downstream proteins such as FANCD1/BRCA2, FANCJ/BRIP1 and FANCN/PALB2 have been linked to elevated risk of breast and ovarian cancers." (PMID 20043851, 2009). "In this study, we evaluated the association between SNPs that efficiently tag the common variation in the BRIP1 gene and the risks of breast and ovarian cancer using a case-control study design." (PMID 17342202, 2007). "Although there is no conclusive evidence linking germline BRIP1 mutations to an elevated risk of breast cancer, these mutations are significantly correlated with an absolute lifetime risk of up to 15% for ovarian cancer." (PMID 40800071, 2025). "Our study differs from the research conducted by Manchanda et al31 on the cost-effectiveness of population-based testing for BRCA1, BRCA2, RAD51C (OMIM 602774), RAD51D (OMIM 602954), BRIP1 (OMIM 605882), and PALB2 mutations for preventing breast and ovarian cancer in the following ways." (PMID 38353949, 2024). "The small number of PALB2 mutations limits interpretation; however, RAD51C, RAD51D, and BRIP1 mutations were associated with both high rates of biallelic loss and high GIS, suggesting that these genes might be true drivers of HRD in ovarian cancer." (PMID 39695768, 2024). "In this study, we focused on GC-5′ss-exons of the breast and/or ovarian cancer (BOC) susceptibility genes, i.e., ATM (MIM#607585) exon 50, BRIP1 (MIM#605882) exon 1, and PALB2 (MIM#610355) exon 12, the last of which specifically undergoes skipping as a frequent alternative splicing event." (PMID 39518003, 2024). "Moreover, a recent meta-analysis provided evidence supporting the pathogenicity of BRIP1, RAD51C, and RAD51D mutations in relation to ovarian cancer, cumulatively contributing to ~2% of ovarian cancer cases." (PMID 37444530, 2023). "In addition, BRCA1/2, ATM, BRIP1, PALB2, RAD51C, and RAD51D gene mutations are reported to be associated with high risk of ovarian cancers, and from the results of tumor tissue, it is easy to further determine their genetic status." (PMID 35186721, 2022).
ovarian carcinoma (continued). "This suggests that panel testing may help guide treatment selection for women with ovarian cancer by identifying PVs in BRIP1, RAD51C, or RAD51D." (PMID 33926482, 2021). "PVs in BRIP1 were identified in 0.8% (233/27,915) of women with ovarian cancer." (PMID 33926482, 2021). "The level of ovarian cancer risk conferred by these mutations is relatively high, indicating that after BRCA1 and BRCA2, the BRIP1, RAD51C, and RAD51D genes are the most important ovarian cancer risk genes, cumulatively contributing to ~ 2% of ovarian cancer cases." (PMID 32359370, 2020). "Lastly, BRIP1, which interacts with and is necessary for the function of BRCA1, is a tumour suppressor, and loss-of-function germline mutations increase the risk of breast and ovarian cancers." (PMID 31870430, 2019). "Population panel testing for BRCA1/BRCA2/RAD51C/RAD51D/BRIP1/PALB2 gene mutations is the most cost-effective genetic-testing strategy in general-population women and can prevent thousands more breast and ovarian cancers than current clinical-criteria based approaches." (PMID 30400647, 2018). "For model development, genetic data will involve genetic testing of high penetrance genes associated with hereditary breast and ovarian cancer, BRCA1 and BRCA2, as well as lower penetrance genes associated with ovarian cancer susceptibility, BRIP1, RAD51C and RAD51D." (PMID 25391615, 2015). "Interestingly, one Fanconi anemia patient has been found to carry a homozygous truncating XRCC2 mutation while biallelic mutations in four breast and ovarian cancer susceptibility genes, BRCA2, BRIP1, PALB2, and RAD51C, are associated with Fanconi anemia." (PMID 25918678, 2015). "Sixteen different FA genes have now been identified whose products act in a common pathway of DNA interstrand crosslink repair, and some of them (including BRCA2/FANCD1, BRIP1/FANCJ, PALB2/FANCN, and RAD51C/FANCO) have also been described as breast and ovarian cancer susceptibility genes." (PMID 24465539, 2014). "After BRCA2/FancD1, two other genes, namely, BRIP1/FancJ and PALB2/FancN, were described as FA and breast and ovarian cancer susceptibility genes, suggesting a strong genetic connection between FA and hereditary breast and ovarian cancer." (PMID 23344037, 2013). "Moreover, rare BRIP1 mutations have been identified in Spanish and Icelandic ovarian kindreds, indicating that BRIP1 behaves like a classical tumor suppressor gene in ovarian cancer." (PMID 23586058, 2013). "Biallelic or in the case of FA-B hemizygous mutations in any one of the underlying genes lead to FA, while monoallelic mutations in FANCD1 (BRCA2), FANCJ (BRIP1), FANCN (PALB2) or FANCO (RAD51C) increase the risk of carriers for developing breast and ovarian cancer." (PMID 23285130, 2012). "FANCJ, also known as BRIP1 (for BRCA1-interacting protein 1) or BACH1 (BRCA1-associated C-terminal helicase 1), belongs to super-family 2 (SF2) Iron–Sulfur (Fe–S) cluster-containing DNA helicases, and is frequently mutated in breast and ovarian cancers, as well as in many other tumor types." (PMID 38177925, 2024). "Germline mutations in BRIP1 are associated with a moderate increase in the risk of epithelial ovarian cancer (EOC), which may have implications for risk prediction and prevention approaches for ovarian cancer." (PMID 39767562, 2024). "More recent studies have improved our understanding of inherited ovarian cancer risk beyond BRCA-related HBOC, and have allowed more detailed estimates of ovarian cancer risk for several homologous recombination (HR)-related genes with moderate-penetrance such as BRIP1, RAD51C/D, PALB2, and ATM." (PMID 35163487, 2022). "BRIP1 pathogenic germline variants may play a causal role in CRC as moderate cancer susceptibility alleles, with association to hereditary CRC predisposition, which could elevate the risk of developing hereditary ovarian cancer." (PMID 36482360, 2022).
ovarian carcinoma (continued). "In addition, it is well known that some HRR genes such as BRCA1/2, ATM, BRAD1, BRIP1, PALB2, RAD51C, and RAD51D are associated with high risk of ovarian cancers, and tissue detection might be a good way to learn the germline status." (PMID 35186721, 2022). "In addition, 13.1% (233/1779) of women with a PV in BRIP1 had a personal history of ovarian cancer." (PMID 33926482, 2021). "Germline mutation of BRIP1 has been show to increase the risk of hereditary ovarian cancer, although the BRIP1 NECC mutation we observed was not clearly pathogenic and that tumor did not exhibit mutational signatures consistent with a defect in homologous recombination." (PMID 32544169, 2020). "Importantly, mono-allelic mutations in certain FA genes including FANCD1 (BRCA2), FANCS (BRCA1), FANCN (PALB2), FANCM, FANCJ (BRIP1), and FANCO (RAD51C) that are believed to operate downstream in the pathway and implicated in HR are associated with sporadic breast and ovarian cancer." (PMID 30813363, 2019). "The aim of this study was to evaluate the expression of BRIP-1 (FANCJ) and FANCI proteins in ovarian cancer tissue and to assess these expressions in differentiating the described clinical features." (PMID 39767562, 2024). "In the course of our study, the ovarian cancer gene panel consisted of the five core genes (BRCA1, BRCA2, BRIP1, RAD51C and RAD51D), and it is likely that the gene panel will be expanded with other cancer genes, such as PALB2, in the near future." (PMID 34617209, 2022). "However, some women at increased risk of ovarian cancer may not be at increased risk of breast cancer, such as BRIP1 carriers or women with Lynch syndrome." (PMID 34672090, 2022). "PVs in BRIP1, RAD51C, or RAD51D were identified in 0.5% of all tested women but in 1.6% of women with a history of ovarian cancer (~ 3-fold increase)." (PMID 33926482, 2021). "For example, the BARD1 and NBN (miR-548ai targets), BRIP1 (miR-567 target), and CHEK2 (miR-943 target) genes, which are known to be involved in breast and ovarian cancers." (PMID 34768979, 2021). "Some of these downstream FA genes are known as tumor suppressor genes in other monoallelic inherited cancers like breast and ovarian cancer (FANCD1 = BRCA2, FANCS = BRCA1, FANCN = PABLB2, FANCJ = BRIP1, FANCO = RAD51C)." (PMID 32397406, 2020). "For BRIP1 and RAD51C, the median age at ovarian cancer diagnosis was after 60 years." (PMID 33926482, 2021). "Finally, two patients harbored a PV in BRIP1, although neither had a personal or family history of ovarian cancer (OC)." (PMID 40361347, 2025). "However, our patient with a VUS in BRIP1 gene at c.3103 C > T did not have a personal or family history of ovarian cancer." (PMID 37277882, 2023). "BRCA1 interacting helicase 1 (BRIP1), an ATP-dependent DNA helicase which belongs to an Iron-Sulfur (Fe-S) helicase cluster family with a DEAH domain, plays a key role in DNA damage and repair, Fanconi anemia, and development of several cancers including breast and ovarian cancer." (PMID 37153833, 2023). "Other mutations were uniquely enriched in HRD+ predicted cases of breast and ovarian cancers (BARD1, BRIP1, MRE11, RAD51D) and cancer cohorts outside breast and ovarian cancer (RAD51B), suggesting additional unique drivers of HRD that may be cancer-cohort specific." (PMID 35643464, 2022).